IL6 (interleukin 6)
Diseases named in the same sentence as IL6 in open-access papers (continued):
Sharing a sentence is not in itself a finding about the gene and the disease.
Incisional hernia (1 paper, 2020). An abdominal hernia that occurs at a site of weakness in the abdominal wall resulting from an incompletely-healed surgical wound. "However, the studies did not focus on the effect of suturing techniques on IL-6 expression in the prevention of incisional hernia, so accordingly, this study aimed to compare the effects of the large stitch with the small stitch technique for abdominal fascial closure on IL-6 expressions in rats." (PMID 33126892, 2020). "The expressions of IL-6 are similar between the small and the large stitch groups, implying that different suturing techniques might not have an impact on the incisional hernia occurrence." (PMID 33126892, 2020). "In conclusion, the IL-6 expressions are similar between the small and the large stitch groups, implying that different suturing techniques might not have an impact on the incisional hernia occurrence." (PMID 33126892, 2020).
infectious colitis (1 paper, 2024). A viral or bacterial infectious process affecting the large intestine. "In an in vivo infectious colitis model, administration of selected C1 coumarin derivatives reduced pathogen loads, the number of inflammatory immune cells (Th1 cells and Th17 cells), and inflammatory cytokine levels (IL-6 and IL-1b) in the intestinal tissue after pathogen infection." (PMID 39081865, 2024).
insulin-resistant diabetes (1 paper, 2016). "In hamsters with fructose feeding induced insulin-resistant diabetes, the serum levels of TNF-a and IL-6 were found to be significantly higher compared with those of the chow-fed hamsters." (PMID 27525022, 2016).
Interstitial pneumonitis (1 paper, 2021). "Furthermore, lymphocytes, neutrophils, and monocytes act dynamically to produce immune-mediated interstitial pneumonitis, with inflammation and activation of subsequent cytokines, such as IL-1, IL-6, IL-8, IL-21, TNF-β, and MCP-1, at the site of infection." (PMID 34451520, 2021).
IPEX syndrome (1 paper, 2025). "At age 14, autoantibodies against IFN-α, which have been described in patients with IPEX syndrome, were only weakly positive, whereas anti-IL-6 autoantibodies were strongly positive." (PMID 40977713, 2025). "A key immunological finding was the presence of likely neutralizing anti-IL-6 autoantibodies which, to the best of our knowledge, have never been reported in patients with IPEX syndrome." (PMID 40977713, 2025).
iridocyclitis (1 paper, 2024). "Similarly, in iridocyclitis, elevated levels of TNF-α and IL-6 in the aqueous humor suggest a role in ocular inflammation." (PMID 39612419, 2024).
ischemic colitis (1 paper, 2020). Inflammation of the colon due to colonic ischemia resulting from alterations in systemic circulation or local vasculature. "In the present study, treatment with PDRN effectively suppressed ischemic colitis-induced COX-2, TNF-α, IL-1β, and IL-6 expressions in the colonic tissues." (PMID 32149087, 2020). "Induction of ischemic colitis increased TNF-α, IL-1β, and IL-6 expressions, whereas decreased adenosine A2A receptor expression (P < 0.05)." (PMID 32149087, 2020). "Expressions of inflammatory cytokines (TNF-α, IL-1β, and IL-6) and inflammatory mediator (COX-2) were upregulated in the ischemic colitis rats." (PMID 32149087, 2020). "Induction of ischemic colitis increased the expressions of inflammatory proteins, such as COX-2 (70–72 kDa), TNF-α (17 kDa), IL-1β (17 kDa), and IL-6 (22–27 kDa) in the colonic tissue (P < 0.05)." (PMID 32149087, 2020). "In the case of PDRN + DMPX treatment, TNF-α, IL-1β, and IL-6 levels were not changed compared to ischemic colitis-induced group." (PMID 32149087, 2020).
keratinocyte carcinoma (1 paper, 2021). A skin cancer arising from the keratin-producing cells of the epidermis. "The pro-inflammatory cytokines IL-6, IL-8, and TNFα possess cancer-promoting functions and are commonly overexpressed in many malignancies including keratinocyte cancers." (PMID 35145494, 2021).
kidney tumor (1 paper, 2024). "Here, we have investigated the activation of the JAK-STAT signaling pathway in three pediatric kidney tumor cell lines (WT-CLS1, WT-3ab and G-401) and demonstrated that several STAT proteins are activated in these cell lines in response to IFN-α, IFN-γ, IL-6 and IL-4." (PMID 38396958, 2024).
Kindler syndrome (1 paper, 2023). Kindler syndrome (KS) is the fourth major type of epidermolysis bullosa (EB), besides simplex, junctional and dystrophic forms, and is characterized by skin fragility and blistering at birth followed by development of photosensitivity and progressive poikilodermatous skin changes. "Of note is the observation that IL-6 secretion is also increased from keratinocytes from Kindler syndrome patients that lack Kindlin-1, although its function is not known." (PMID 36883731, 2023).
Krabbe disease (1 paper, 2005). A lysosomal disorder that affects the white matter of the central and peripheral nervous systems. "Since inducible nitric oxide (iNOS) and IL-6 were strongly upregulated in twi/twi and Krabbe's disease, the positive effect of ibudilast may be also associated with suppression of iNOS and IL-6, and enhancement of inhibitory cytokines and neurotrophic factors." (PMID 15813970, 2005).
large cell lung cancer (1 paper, 2022). "Among these, IL-6 has been established as a potent independent risk factor for OS in early-stage LUSC patients, and patients with higher levels of IL-6 expression tend to have advanced LUSC and large cell lung cancer." (PMID 36523974, 2022).
laryngeal papilloma (1 paper, 2015). "One study identified elevated levels of the cytokines interleukin-6 (IL-6), interleukin-8 (IL-8), and VEGF in patients with HNSCC compared to patients with laryngeal papilloma or age-matched controls." (PMID 26098778, 2015).
leiomyosarcoma (1 paper, 2022). An uncommon, aggressive malignant smooth muscle neoplasm, usually occurring in post-menopausal women. "Compared to other histological types, leiomyosarcoma showed high expression of HELLS, EPAS1, NQO1 and low expression of IL6." (PMID 34982796, 2022).
Leukoencephalopathy (1 paper, 2024). This term describes abnormality of the white matter of the cerebrum resulting from damage to the myelin sheaths of nerve cells. "The abundance of mutated F. varium positively correlated with IL-1 β and IL-6 levels in patients with cerebral autosomal dominant arteriopathy with subcortical infarcts and leukoencephalopathy." (PMID 39114506, 2024).
lichen sclerosus (1 paper, 2022). "However, there is almost no data reflecting the expression of cytokines genes in the LS tissue what prompted us to determine the mRNA levels of IL-1A, IL-6, IL-1B, IL-1RN, TGF-β1 and INF-γ genes in a large sample of penile lichen sclerosus tissue as compared to control penile tissues." (PMID 35103930, 2022).
lipidosis (1 paper, 2017). "Moreover, adipocytokines IL6 and Leptin, in addition the genes, EGR1, FOS, SERPINE1, AGT and MMP2 might have great impacts on adipocyte differentiation and lipidosis." (PMID 28706200, 2017).
Lipoatrophy (1 paper, 2021). Localized loss of fat tissue. "Opposing such findings, the literature reports an increase in the expression of IL-6 and TNF-α in PLWHA diagnosed with lipoatrophy." (PMID 34957175, 2021).
liver tumors (1 paper, 2023). "A dose of NDEA of 200 mg/kg has been reported to induce liver tumors and could incite chronic inflammation, elevating levels of interleukin-1β (IL-1β), interleukin-6 (IL-6), and tumor necrosis factor-α (TNF-α), and thereby attracting immune cells to the liver tissue." (PMID 37759689, 2023).
lower limb ulcers (1 paper, 2023). "We also showed that patients with diabetic foot, compared to diabetic patients without lower limb ulcers and healthy controls, have higher serum levels of inflammatory molecules, such as HIF-1alpha and VEGF, and comparable levels of IL-6, TNF-alpha and eNOS." (PMID 37365645, 2023).
lumbar spinal stenosis (1 paper, 2022). A spinal stenosis that involves the lumbar region of vertebral column. "In addition, IL-6 mRNA and protein expression was increased in the hypertrophied LF in patients with lumbar spinal stenosis." (PMID 35563428, 2022).
Luminal Breast Cancer (1 paper, 2024). "Luminal breast cancer is an epithelial type; however, the cytokine IL-6, secreted by cells within the tumor microenvironment, stimulates the epithelial-to-mesenchymal transition (EMT) and promotes metastasis." (PMID 39201674, 2024).
lupus-like syndromes (1 paper, 2025). "While IL-6 (eg, tocilizumab) and TNF-α inhibitors show promise, they involve risks such as infections and lupus-like syndromes." (PMID 40643149, 2025).
lymphangiectasia (1 paper, 2014). "g. tumor necrosis factor-α and interleukin-6) vascular or mucosal damage, and ruptured mucosal lacteals resulting in lymphangiectasia." (PMID 25490025, 2014).
lymphangioleiomyomatosis (1 paper, 2014). A multifocal neoplasm with perivascular epithelioid cell differentiation affecting almost exclusively females of child-bearing age. "Lymphangioleiomyomatosis/TSC cells secrete, probably in a tuberin-dependent manner, high amounts of IL-6 and IL-8 that cannot be significantly affected by the exposure to rapamycin or anti-EGFR antibodies." (PMID 24606538, 2014).
mast cell leukemia (1 paper, 2016). Mast cell leukemia is a malignant form of systemic mastocytosis (SM) characterized, most of the time, by the presence of circulating mast cells. "Even though this mouse model represents ASM/mast cell leukemia when fully manifested, the accumulation of transformed mast cells is progressive and the associated changes in circulating ROS, DJ-1, and IL-6 at the initial stages parallel the changes observed in ISM." (PMID 27611333, 2016).
mastocytoma (1 paper, 2016). A localized tumor composed of sheets of mast cells without atypia. "Similarly, murine mastocytoma mast cells (P815) carrying a D814Y mutation in KIT analogous to the human D816V mutation, constitutively produced high levels of IL-6, while normal BMMC did not." (PMID 27611333, 2016).
meningococcemia (1 paper, 2018). "The involvement of cytokines, and more particularly interleukin-6, has been suggested to explain the pathogenesis of myocardial dysfunction in meningococcemia." (PMID 30050613, 2018).
Meningothelial Meningioma (1 paper, 2021). A WHO grade I meningioma characterized by the presence of tumor cells that form lobules. "The c.236A>C variant has already been described in meningothelial meningioma and is associated with IL-6 signaling pathways and DNA damage response." (PMID 33503190, 2021).
Menstrual disorder (1 paper, 2022). Category of disorders related to menstruation. "Moreover, Belimumab group treatment significantly reduced the serum levels of IL-6, the ratio of B and T cells, and the proportion of infections and menstrual disorders." (PMID 35979351, 2022).
methylmalonic acidemia (1 paper, 2022). A genetically heterogenous inherited disorder characterized by abnormalities in the metabolism of lipids and proteins. "IL-6 was also recently reported to be increased in the serum of methylmalonic acidemia patients." (PMID 36266345, 2022).
microtia (1 paper, 2025). "Moreover, the expression of IL-6 was negatively associated with microtia severity." (PMID 40809693, 2025). "In summary, these results suggest that IL-6 is a biomarker and potential therapeutic target for microtia." (PMID 40809693, 2025). "IL-6 is a potential biomarker and preventive and therapeutic target for microtia." (PMID 40809693, 2025). "Finally, we constructed a mouse model of congenital microtia and used an IL-6 overexpression vector constructed using AAV to conduct preventive intervention in pregnant mice, and found that IL-6 is a potential therapeutic target for microtia." (PMID 40809693, 2025). "Moreover, we screened 37 genes as potential diagnostic biomarkers for microtia through SVM-RFE and intersected them with 15 hub genes to obtain two specific biomarkers (IL-6 and CXCL1) in microtia." (PMID 40809693, 2025). "IL-6 is a potential biomarker and preventive and therapeutic target for microtia patients." (PMID 40809693, 2025). "The use of IL-6 for the clinical treatment or prevention of microtia has not been specifically discussed in this article, especially regarding the selection of its therapeutic concentration." (PMID 40809693, 2025). "However, the role of IL-6 in the microtia has not yet been studied." (PMID 40809693, 2025).
Middle ear cholesteatoma (1 paper, 2020). "Middle ear cholesteatoma stem cells (ME-CSCs) showed a significantly increased expression of TLR4 accompanied by a significantly enhanced LPS-dependent pro-inflammatory gene expression pattern of TNFα, IL-1α, IL-1ß, IL-6, and IL-8 compared to non-pathogenic control cells." (PMID 31947538, 2020).
mitral annular calcification (1 paper, 2016). "It is worth noting that IL-6 is associated with heart valve calcification in general and with mitral annular calcification in particular." (PMID 27589735, 2016).
motor neuron degeneration (1 paper, 2021). "Further study is needed to clarify the relationship between CSF ATP levels and several inflammatory cytokines such as TNF-α, IL-6, and COX-2 as well as between CSF ATP levels and blood or CSF NfL, which reflect motor neuron degeneration in patients with ALS." (PMID 34193068, 2021).
Moyamoya disease (1 paper, 2023). Moyamoya disease (MMD) is a rare intracranial arteriopathy involving progressive stenosis of the cerebral vasculature located at the base of the brain causing transient ischemic attacks or strokes. "Multivariate stepwise regression analysis indicated that the G3 subgroup of IL-6 and the G4 subgroup of TNF-α were the independent risk factors for adverse prognosis in adults with moyamoya disease (OR 3.678, 95% CI [1.491, 9.074], p = 0.005; OR 2.996, 95% CI [1.180, 7.610], p = 0.021)." (PMID 36769472, 2023). "IL-6 and TNF-α were associated with poor prognosis in adult patients with moyamoya disease." (PMID 36769472, 2023).
mucinous neoplasm (1 paper, 2025). "CRP and IL-6 levels among inflammatory markers were significantly higher in the mucinous neoplasm group." (PMID 41451009, 2025).
mucoepidermoid carcinoma (1 paper, 2015). A carcinoma morphologically characterized the presence of cuboidal mucous cells, goblet-like mucous cells, squamoid cells, cystic changes, and a fibrotic stromal formation. "To begin to understand the therapeutic potential of targeting IL-6 signaling in mucoepidermoid carcinomas, we evaluated the expression of key components of the IL-6 pathway in primary human tumors and in our xenograft models." (PMID 26287605, 2015). "However, it is unclear if IL-6 signaling is involved in the survival of cancer stem cells and the resistance to chemotherapy observed in patients with mucoepidermoid carcinoma." (PMID 26287605, 2015). "IL-6 is clearly not the only endothelial cell-derived factor that could potentially affect the behavior of mucoepidermoid carcinoma cells." (PMID 26287605, 2015). "However, we do not know the effect of inhibition of IL-6 signaling in mucoepidermoid carcinomas." (PMID 26287605, 2015).
myoma (1 paper, 2021). "It was emphasized that vitamin D can act as an inflammatory suppressant by diminishing the production of pro-inflammatory cytokines, including TNFα and IL6, in myoma." (PMID 34442017, 2021). "Our study results demonstrated significant reduction in the expression of inflammatory cytokines IL6 and IL10, influenced by UPA therapy, when a substantial decrease in myoma volume after treatment was observed." (PMID 34442017, 2021).
myopericytoma (1 paper, 2025). A usually slow growing, subcutaneous nodular neoplasm arising from myopericytes. "A growing body of work suggests that myopericytomas may share certain inflammatory or myofibroblastic pathways seen in conditions like DD, given the mutual expression of alpha-smooth muscle actin and involvement of inflammatory cytokines (TNF-α, IL-6)." (PMID 40507464, 2025).
myotonic dystrophy (1 paper, 2024). An inherited progressive disorder affecting the muscles. "Senescent cells inhibit the differentiation of myoblasts by secretion of IL6 by senescent muscle stem cells in myotonic dystrophy." (PMID 39196610, 2024).
neonatal encephalopathy (1 paper, 2020). "Rapid increases in the levels of the main inflammatory cytokines TNF-α, IL-1β, and IL-6 under oxidative stress cause direct injury to the ischemic site and positively correlate with the severity of neonatal encephalopathy." (PMID 32074976, 2020).
Neurofibrillary tangles (1 paper, 2021). Pathological protein aggregates formed by hyperphosphorylation of a microtubule-associated protein known as tau, causing it to aggregate in an insoluble form. "Tellingly, IL-1β and IL-6 in the brain of AD patients restrain the function of cholinergic systems and activate Aβ aggregation, leading to the accumulation of neurofibrillary tangle (NFT)." (PMID 34065080, 2021).
neurofibromatosis type 1 (1 paper, 2024). A clinically heterogeneous, neurocutaneous genetic disorder characterized by cafe-au-lait spots, iris Lisch nodules, axillary and inguinal freckling, and multiple neurofibromas. "The regulation of IL-6 production is often linked to genetic factors, including the presence of certain genetic syndromes such as neurofibromatosis type 1 (NF1)." (PMID 38396821, 2024).
Neurogenic bladder (1 paper, 2023). A type of bladder dysfunction caused by neurologic damage. "Some case reports have measured inflammatory biomarkers when treating with Lactobacillus rhamnosus GR-1 and Lactobacillus reuteri RC-14, resulting in attenuated expression of TNF-α, IL-6, IL-8, IL-10 and IL-12 (p70) in the neurogenic bladder of SCI patients with UTIs." (PMID 37291666, 2023).
new-onset refractory status epilepticus (1 paper, 2025). "Early clinical signals (e.g., IL-1/IL-6 pathway agents in New Onset Refractory Status Epilepticus (NORSE)/febrile infection-related epilepsy syndrome (FIRES)) and robust preclinical data support continued translational work." (PMID 41458814, 2025).
ocular melanoma (1 paper, 2021). A melanoma that arises from the structures of the eye or ocular adnexa. "For instance, ocular melanoma showed a strong downregulation of IL6 expression levels comparing to normal tissue (GTEx normal skin) in contrast with literature." (PMID 34576335, 2021).
olfactory neuroblastoma (1 paper, 2023). An olfactory neuroblastoma arising in the paranasal sinus. "A previous study reported that genes associated with the IFN-α response, IL2-STAT5, and IL6-JAK-STAT3 signaling pathways were enriched in tumors of patients with recurrent olfactory neuroblastoma." (PMID 36867313, 2023).
oligospermia (1 paper, 2025). Decreased number of spermatozoa in the semen. "Results showed that the levels of IL-6 and IL-1β in oligospermia samples were elevated compared to those in normal samples." (PMID 40707433, 2025).
opioid dependence (1 paper, 2024). "Our study suggests that withdrawal in individuals with opioid dependence who are also HIV-infected dysregulates the HPA axis, negatively affects cognitive function, induces dysphoric symptoms, and is associated with a rise in the inflammatory marker IL-6." (PMID 38257791, 2024).
Orofacial dyskinesia (1 paper, 2023). "With IL-6, the relationship with current orofacial dyskinesia is considerably less certain, but an association does exist in the mouse with the expression of this cytokine in the striatum." (PMID 37810262, 2023). "Although rodent studies are somewhat inconsistent, all but two in mice reported increased striatal IL-6 levels in haloperidol -induced or reserpine -induced orofacial dyskinesia." (PMID 37810262, 2023). "However, in two studies co-treatment with antioxidants (isoflavones, cannabidiol) did not reduce IL-6 levels and in two studies striatal IL-6 levels did not correlate with the frequency of orofacial dyskinesia." (PMID 37810262, 2023).